RNU6-689P (RNA, U6 small nuclear 689, pseudogene)
Gene: Small nuclear RNA gene on chromosome 14 (75,020,761 to 75,020,867, forward strand). Ensembl gene ENSG00000206924.
Homologues: Orthologues: chimpanzee U6 (99% identical), macaque U6 (87% identical). Paralogues in human: RNU6-1145P (89% identical), RNU6-1316P (89% identical), RNU6-20P (88% identical), RNU6-35P (88% identical), RNU6-477P (88% identical), RNU6-188P (87% identical), RNU6-211P (87% identical), RNU6-25P (87% identical), RNU6-283P (87% identical), RNU6-38P (87% identical), RNU6-393P (87% identical), RNU6-41P (87% identical), and 1283 more.